ATXN1 (ataxin 1)
Diseases named in the same sentence as ATXN1 in open-access papers (continued):
Sharing a sentence is not in itself a finding about the gene and the disease.
Ataxia (continued). "Furthermore, knockout of both calbindin and parvalbumin in ataxin-1-expressing mice resulted in an exacerbated the phenotype, producing severe ataxia and altered Purkinje cell morphology." (PMID 32765211, 2020). "However, we only observed a subtle induction of Atxn1, and overexpression of wild-type Atxn1 does not cause ataxia and Purkinje cell loss to the extent we see in our Ronin transgenic mouse line." (PMID 34165550, 2021). "Our novel observation that DNAJA3 shows significantly enriched interaction with disease proteins that are responsible for spinocerebellar ataxia, including the nuclear transcription modulator ATXN1 or the cytosolic stress response factor ATXN3, might be viewed in this context." (PMID 34345994, 2021). "Repeat expansions, such as those in HTT (CAG repeats in Huntington’s disease), ATXN1 and ATXN2 (CAG repeats in spinocerebellar ataxias), and FXN (GAA repeats in Friedreich’s ataxia), are well-established causes of neurodegenerative disorders." (PMID 40166539, 2025). "This study involved six genes (ATXN1, ATXN3, ATXN7, HTT, NOP56, and PPP2R2B), while a higher detection rate has been reported in a spinocerebellar ataxia cohort (4.4%, 22/498), which included five genes (ATXN2, ATXN3, NOP56, AR and HTT)." (PMID 38308084, 2024). "For example, Huntingtin (HTT; Huntington's Disease), Frataxin (FXN; Friedreich Ataxia), and Ataxin 1/2 (ATXN1/ATXN2; Spinocerebellar Ataxias) all have GC-rich trinucleotide expansion tracks that form R-loops in vitro and associate with disease progression." (PMID 31225499, 2019). "Patient P-1 carried 43 repeats of the ATXN1 gene and showed tremors in the upper limbs as the sole symptom for the duration of 30 years without developing ataxia." (PMID 38961870, 2024). "The use of the gene editing system in dominantly inherited ataxias like SCA1, where the polyQ expansion in exon 8 of ATXN1 leads to a gain of toxic protein function, may be the only definitive solution for these kinds of neurodegenerative diseases." (PMID 36434031, 2022). "A disrupted TAD boundary was recently identified at the repeat region of the ATXN1 gene in SCA1 patients but an understanding of the chromatin regulation of the other spinocerebellar ataxia-causing genes remains lacking." (PMID 35592702, 2022). "The induction of Atxn1 was an interesting finding because studies have shown that an increase of wild-type Atxn1 protein can induce ataxia in mice even in the absence of a polyQ expansion through a gain of function of the Atxn1-Cic complex." (PMID 34165550, 2021). "Regarding the underlying molecular mechanism, the concept that polyQ expansion causes ataxia largely through a toxic gain-of-function mechanism is supported by the lack of ataxia in Atxn1 null mice." (PMID 33436887, 2021). "Although Atxn1−/− mice do not exhibit overt ataxia phenotypes or progressive neurodegeneration, they do exhibit a variety of neurological deficits." (PMID 20628574, 2010). "Interestingly, previous work showed that ATXN1–/– mice do not develop ataxia and have a normal life span, indicating that the reduced rescue effect is not attributed to a loss of function of ATXN1." (PMID 33554954, 2021). "However, we have termed a subset of ataxias, not just with reduced IP3R1 but also with supersensitive IP3R1, and regardless of the mutated gene (e.g., ITPR1, Ataxin-1, Ataxin-2, Ataxin-3) as ‘IP3R1-associated ataxias’." (PMID 22703638, 2012).
Huntington disease (19 papers, 2007 to 2025). Huntington disease (HD) is a rare neurodegenerative disorder of the central nervous system characterized by unwanted choreatic movements, behavioral and psychiatric disturbances and dementia. "A-syn brain aggregates are the main inclusions found in Parkinson’s disease brains, whereas huntingtin (Htt), ataxin-1 and ataxin-2 are the main components of Huntington disease, SCA1 and SCA2, respectively." (PMID 39974178, 2025). "Loss of hsrω-n lncRNA suppressed eye-specific degeneration in a variety of expanded polyQ backgrounds such as the 127Q, ataxin-1 Q82 (SCA1), MJDTR-Q78 (SCA3) or Httex1p Q93 (Huntington’s disease) fly models." (PMID 36675966, 2022). "The CAG repeat is translated into an expanded polyglutamine (polyQ) track in the ATXN1 protein, which places SCA1 into the family of polyglutamine diseases that also includes SCA 2, 3, 6, 7, 17, Kennedy disease, Huntington’s disease, and dentatorubropallidoluysian atrophy." (PMID 29975753, 2018). "Transgenic co-expression of Ku70 was effective for a Huntington's disease (HD) mouse model (R6/2 mice) but not effective for Atxn1-KI." (PMID 25510912, 2015).
amyotrophic lateral sclerosis (12 papers, 2016 to 2025). Amyotrophic lateral sclerosis (ALS) is a neurodegenerative disease characterized by progressive muscular paralysis reflecting degeneration of motor neurons in the primary motor cortex, corticospinal tracts, brainstem and spinal cord. "In 2010, intermediate-length repeat expansions in ATXN2 were reported to be a risk factor for amyotrophic lateral sclerosis, and in 2012, the same was reported for ATXN1." (PMID 38585669, 2024). "Since the majority of alleles (158/176) showed plus one repeat for ATXN1 with ExpansionHunter compared to PCR analysis, all amyotrophic lateral sclerosis patients and controls were adjusted accordingly with minus one repeat for ATXN1 in the logistic regression analysis." (PMID 38585669, 2024). "IAs in the ATXN2 and ATXN1 genes may cause amyotrophic lateral sclerosis, and grey zone alleles of the FMR1 have been associated with parkinsonism." (PMID 38433266, 2024). "In ATXN1, 50 amyotrophic lateral sclerosis patients (12.1%) and 96 controls (13.5%) carried ≥33 repeats (P = 0.753)." (PMID 38585669, 2024). "Using an exome sequencing approach with ExpansionHunter, we investigated a Norwegian amyotrophic lateral sclerosis cohort for repeat expansions in AR, ATXN1, ATXN2 and HTT." (PMID 38585669, 2024). "Repeat expansions in ATXN1 (≥33 repeats) were carried by 50 amyotrophic lateral sclerosis patients." (PMID 38585669, 2024). "Norwegian amyotrophic lateral sclerosis patients (n = 414) and neurologically healthy controls adjusted for age and gender (n = 713) were investigated for repeat expansions in AR, ATXN1, ATXN2 and HTT using short read exome sequencing and the ExpansionHunter software." (PMID 38585669, 2024).
glioma (11 papers, 2020 to 2025). A benign or malignant brain and spinal cord tumor that arises from glial cells (astrocytes, oligodendrocytes, ependymal cells). "The study of other splicing factors implicated in aberrant splicing indicated that SRSF10, which is upregulated in glioma-associated endothelial cells, contributes to this process by promoting the biogenesis of circular-ataxin 1 (circ-ATXN1) biogenesis." (PMID 39915450, 2025). "Circ-ATXN1 were significantly upregulated in glioma-associated endothelial cells in comparison with astrocyte-associated endothelial cells (AECs), whereas knockdown of circ-ATXN1 significantly inhibited endothelial cell viability, migration and tube formation." (PMID 34200145, 2021). "In the present study, we have verified that circ-ATXN1 is overexpressed in glioma-associated endothelial cells (GECs)." (PMID 32600379, 2020). "The potential function of SRSF10/circ-ATXN1/miR-526b-3p axis in glioma-associated endothelial cells (GECs) angiogenesis was further studied." (PMID 32600379, 2020). "Circ-ATXN1, within an RNA-induced silencing complex, sequesters miR-526b-3p to modulate glioma angiogenesis." (PMID 40303323, 2025). "Knockout of circ-ATXN1 can significantly inhibit cell viability, migration and tube formation of gliomas." (PMID 34616746, 2021). "We further investigated SRSF10/ circ-ATXN1/ miR-526b-3p axis on glioma angiogenesis, in order to provide new theoretical and experimental basis in regulating glioma angiogenesis." (PMID 32600379, 2020). "More importantly, knockdown of circ-ATXN1 combined with miR-526b-3p significantly reduced the hemoglobin content on glioma angiogenesis in vivo." (PMID 32600379, 2020). "This study elaborated the critical regulatory effects of SRSF10/circ-ATXN1/miR-526b-3p pathway on glioma angiogenesis." (PMID 32600379, 2020). "We established glioma cell lines stably expressing circ-ATXN1 knockdown with up-regulation and down-regulation of miR-526-3p." (PMID 32600379, 2020). "SRSF10 enhances circ-ATXN1 production in glioma by binding its 5' and 3' ends." (PMID 40303323, 2025). "Thus, we presume that circ-ATXN1 participates in the regulation of glioma angiogenesis and the specific mechanism of circ-ATXN1 function needs further exploration." (PMID 32600379, 2020). "Thus, we hypothesized that circ-ATXN1 was involved in SRSF10-mediated regulation on glioma angiogenesis." (PMID 32600379, 2020). "The knockdown of SRSF10 and circ-ATXN1 significantly reduced GEC proliferation, migration, and tube formation in vitro and reduced glioma angiogenesis in vivo." (PMID 39915450, 2025). "In summary, we discovered the molecular regulatory network in which SRSF10 facilitated circ-ATXN1 biogenesis and subsequently increased its binding with miR-526b-3p to inhibit the negative regulatory effect of miR-526b-3p on MMP2 and VEGFA in regulating glioma angiogenesis." (PMID 32600379, 2020). "No research about circ-ATXN1 and miR-526-3p on glioma angiogenesis has been conducted." (PMID 32600379, 2020). "Hence, we further determined that circ-ATXN1, rather than linear ATXN1, exerted effects on glioma angiogenesis." (PMID 32600379, 2020). "In contrast to glioma stem cells, U87 cells showed no overexpression of stem cell markers, such as SOX2, ZEB1, ATXN1, ALCAM, CD9, ITGA7, CD44 and CHI3L1." (PMID 34680293, 2021).
Alzheimer disease (9 papers, 2007 to 2025). A progressive, neurodegenerative disease characterized by loss of function and death of nerve cells in several areas of the brain leading to loss of cognitive function such as memory and language. "MiR-19b is also associated with many neurological diseases, including Alzheimer’s disease and Parkinson’s disease, through its interactions with key targets such as Pten and Atxn1." (PMID 40057637, 2025). "Conversely, ATXN1 loss-of-function is involved in Alzheimer’s disease (AD) and tumorigenesis." (PMID 33478569, 2021). "In addition to delivery of the ASO to the brain, targeting ATXN1 using RNA therapy faces another challenge, as a complete loss of ATXN1 may contribute to Alzheimer’s disease by increasing the transcription of BACE1, which encodes for the ß-secretase enzyme." (PMID 37238658, 2023). "This is consistent with recent studies indicating loss of ATXN1 as a risk factor for Alzheimer’s disease and showing that a decrease in ATXN1 contributes to Alzheimer’s disease pathology." (PMID 33436887, 2021). "Large intact cytoplasmic IBs of DsRed1-E5-ataxin-1 frequently deformed the nuclear envelope (inset), in common with nuclear pore complexes seen in Alzheimers disease." (PMID 17925862, 2007).
dentatorubral-pallidoluysian atrophy (9 papers, 2007 to 2022). Dentatorubral pallidoluysian atrophy (DRPLA) is a rare subtype of type I autosomal dominant cerebellar ataxia (ADCA type I). "For ataxias SCA1, SCA2, SCA3, SCA6, SCA7, SCA17 and dentatorubral-pallidoluysian atrophy, expansion beyond 39, 33, 45, 20, 34, 41, and 35 repeats in the ATXN1, ATXN2, ATXN3, CACNA1A, ATXN7, TBP, and ATN1 genes, respectively, will cause disease." (PMID 35592702, 2022).
Parkinson disease (8 papers, 2012 to 2025). A progressive degenerative disorder of the central nervous system characterized by loss of dopamine producing neurons in the substantia nigra and the presence of Lewy bodies in the substantia nigra and locus coeruleus. "ATXN1 could be a predictor of cancer risk among patients with Parkinson’s disease, suggesting that cancer and neurodegeneration process can share common pathways." (PMID 39974178, 2025). "Besides, ATXN1 could be a predictor of cancer risk among patients with Parkinson’s disease, and these results suggest that cancer and neurodegeneration processes can share common pathways." (PMID 39974178, 2025). "The long ATXN1 allele and the CAG size and both the short and long alleles of ATXN2 were predictor variables of the Parkinson’s disease risk." (PMID 39974178, 2025). "The long ATXN1 and HTT alleles and CAG size and both the ATXN2 short and long alleles were predictors for the Parkinson’s disease risk." (PMID 39974178, 2025). "This study aimed to investigate the influence of CAG repeat sizes in ATXN1, ATXN2 and HTT genes on the risk for developing cancer and Parkinson’s disease in a large cohort of patients with idiopathic Parkinson’s disease and healthy controls." (PMID 39974178, 2025). "We described an association of HTT, ATXN1 and ATXN2 with the risk of Parkinson’s disease, which reinforce the hypothesis of the common pathway of neurodegeneration." (PMID 39974178, 2025). "Future biochemical studies are needed to elucidate whether HTT, ATXN1 and ATXN2 CAG can trigger not only the Htt or ataxin aggregation but also other pathological proteins such as a-syn as well, and this explains their Parkinson’s disease genetic risk." (PMID 39974178, 2025). "Interestingly, all three identified kinases were connected to ataxin-1 through α-synuclein (SNCA), a protein associated with several neurodegenerative diseases and particularly Parkinson’s disease." (PMID 40029919, 2025). "miR-101 targets ataxin 1, responsible for SCA1, at both the mRNA and protein levels; miR-433 targets fibroblast growth factor 20 which induces α-synuclein expression, which was previously shown to cause Parkinson’s disease when overexpressed." (PMID 22844398, 2012). "For ATXN1 gene CAG repeats size, the best logistic model (P = 0.001, AIC = 1666.1) included the quadratic term of short allele (P = 0.024), the long allele (0.021) and the interaction between both alleles (P = 0.017) as predictors for the Parkinson’s disease risk." (PMID 39974178, 2025). "Among the agents able to prevent aggregation of the mutant ataxin-1 and the consequent neurotoxicity, bromocriptine methylate (BRC), a potent DRD2 agonist approved for the treatment of Parkinson’s disease, showed promising results in ALS preclinical studies." (PMID 28236105, 2017). "For the ATXN1 gene, we observed an increased frequency of IAs in patients with Parkinson’s disease compared with controls, but it was not significant [9.5 versus 6.3%, respectively; P = 0.576, OR (95% CI): 0.64 (0.39–1.02)]." (PMID 39974178, 2025). "When we stratified by cancer and non-cancer, we observed a non-statistically significant increased frequency of ATXN1 IAs in the Parkinson’s disease non-cancer group compared with cancer group controls (10.4 versus 5.7%)." (PMID 39974178, 2025). "In that case, the clear pathogenesis of ATXN1-mediated SCA1 may provide insight into the more complex mechanisms of Alzheimer’s and Parkinson’s disease." (PMID 34826062, 2022). "However, we observed a non-significant increased frequency of ATXN1 IAs in the non-cancer patients with Parkinson’s disease compared with the cancer controls [10.4 versus 5.7%; P = 0.19, OR (95% CI): 1.91 (0.961–4.23)]." (PMID 39974178, 2025). "A case–control or cancer–non-cancer Parkinson’s disease comparisons were conducted to examine the size of the HTT, ATXN1 and ATXN2 CAG repeats in the different groups." (PMID 39974178, 2025).
cervical carcinoma (7 papers, 2017 to 2025). A carcinoma arising from either the exocervical squamous epithelium or the endocervical glandular epithelium. "To identify the molecular mechanism underlying cell growth in cervical cancer promoted by ATXN1, we analyzed the relevant regulatory signaling pathways." (PMID 29212253, 2017). "In other words, reduced ATXN1 expression caused EMT in cervical cancer cells." (PMID 34638401, 2021). "The suppression of ATXN1 regulation leads to the induction of epithelial–mesenchymal transition (EMT) in cervical cancer cells." (PMID 41272205, 2025). "Under Hypoxia, NICD overexpression causes degradation of ataxin-1 (ATXN1) by MDM2, thereby enhancing Snail expression to induce EMT in cervical cancer cells." (PMID 41208892, 2025). "ATXN1 regulates epithelial mesenchymal transition (EMT) in cervical carcinoma cells where its depletion promotes migration and invasion." (PMID 36720985, 2023). "Atxn1 has been demonstrated to be involved in tumorigenesis of cervical cancer cells via the EGFR-RAS-MAPK signaling pathway." (PMID 32245399, 2020). "Taken together, these results imply that ATXN1 increased cervical cancer cell tumorigenesis in vivo." (PMID 29212253, 2017). "In the present study, we demonstrate that ATXN1 is involved in cervical cancer tumorigenesis by promoting the proliferation of human cervical cancer cells." (PMID 29212253, 2017). "The analyses revealed that the expression of ATXN1 increased in many of the cervical cancer specimens and correlated with pERK1/2 expression." (PMID 29212253, 2017). "Our tissue microarray analysis showed that the expression of ATXN1 is upregulated in cervical squamous cell carcinoma, which represents the most common type of cervical cancer." (PMID 29212253, 2017). "It has been recently reported that ATXN1 regulates the epithelial–mesenchymal transition of cervical cancer cells." (PMID 29212253, 2017). "Previously, we reported that ATXN1 regulates the epithelial–mesenchymal transition of cervical cancer cells." (PMID 29212253, 2017). "Taken together, these results suggest that ATXN1 knockdown induces EMT in cervical cancer cell lines and that the Snail promoter is a direct target of ATXN1." (PMID 28212558, 2017). "Mouse xenograft tumorigenicity assays showed that ATXN1 downregulation inhibited tumorigenesis in cervical cancer cell lines in nude mice." (PMID 29212253, 2017). "We found that the downregulation of ATXN1 expression induced EMT in cervical cancer cell lines in which the Snail promoter was a direct transcriptional target of ATXN1 and promoted tumor cell migration and invasion." (PMID 28212558, 2017). "Human cervical cancer tissue microarrays and immunohistochemical techniques showed that ATXN1 was significantly upregulated in many such tissues." (PMID 29212253, 2017). "Previously, we reported that ATXN1 plays an important role in the epithelial–mesenchymal transition of cervical cancer cells." (PMID 29212253, 2017). "Our results suggest that ATXN1 plays an important role in cervical cancer tumorigenesis and is a prognostic marker for cervical cancer." (PMID 29212253, 2017). "Surprisingly, we found that the SiHa cervical cancer cell line exhibited a mesenchymal-like morphology following ATXN1 depletion." (PMID 28212558, 2017). "Our results confirm that ATXN1 plays an important role in cervical cancer cell proliferation, and therefore, it is a potential therapeutic target for treating cervical cancer." (PMID 29212253, 2017). "First, we examined ATXN1 expression in HeLa and SiHa cervical cancer cell line cells cultured under normoxic (21% O2) or hypoxic (1% O2) conditions." (PMID 28212558, 2017). "In the present study, we aimed to investigate the functional significance of ATXN1 in cervical cancer via studies of its role in the EMT and tumor development." (PMID 28212558, 2017).